AR (androgen receptor)
Diseases named in the same sentence as AR in open-access papers (continued):
Sharing a sentence is not in itself a finding about the gene and the disease.
tumor (continued). "The fact that knocking down PCA3 reduces AR signaling, as well as cell growth and survival, suggests that modulating AR signaling in tumor cells may be possible by overexpression of PCA3." (PMID 39512820, 2024). "The interaction between AHR and AR signaling pathways might promote tumor growth and lead to resistance to standard treatments." (PMID 39600743, 2024). "To evaluate whether Stat5 signaling is critical for AR mRNA expression in clinical patient-derived PCs, we used an ex vivo 3D tumor explant culture system of patient-derived PCs which we have established and characterized previously." (PMID 38416822, 2024). "Furthermore, AR is an important marker that has previously been correlated with e.g., tumor growth, proliferation, and invasion." (PMID 38286854, 2024). "Interestingly, one complete responder in this trial was a female patient with strong tumor AR expression." (PMID 38398136, 2024). "This leads to enhanced AR signaling, promoting tumor growth and treatment resistance." (PMID 39600743, 2024). "In addition, more studies are required to accurately assess the importance of the expression of PD‐1/PD‐L1/PD‐L2 in tumor cells and tumor‐infiltrating lymphocytes in the context of AR‐NHL in future research." (PMID 38613207, 2024). "Elevated AHR activity, combined with genetic variations and environmental exposures, may amplify AR signaling, leading to more aggressive tumor behavior and resistance to conventional treatments such as ADT." (PMID 39600743, 2024). "In liver metastases, neutrophils aid in tumor cell spread in an androgen receptor-dependent manner." (PMID 39684829, 2024). "Notwithstanding these advancements, some patients experience resistance to existing androgen receptor-targeting therapies, underscoring the need for novel agents that can further enhance clinical outcomes, especially for high-volume cases where the tumor burden is substantial and aggressive." (PMID 39690158, 2024). "However, it was found that mice lacking hepatic AR developed more undifferentiated tumors and larger tumor sizes at the late metastatic stage compared to mouse models expressing AR, and these mice also died earlier due to increased lung metastasis." (PMID 38966543, 2024). "Secondly, the limited information on how BAT affects the localization of AR, AR signaling pathways, or the tumor microenvironment could pose a constraint." (PMID 38255286, 2024). "In PCa, androgen receptor signaling plays a critical role in tumor growth and survival." (PMID 38256166, 2024). "Specifically, SIRT1, SIRT2, SIRT6, and SIRT7 are implicated in promoting PCa progression, while SIRT5 displays a paradoxical role, simultaneously aiding DNA repair and inhibiting apoptosis, yet fostering tumor growth through androgen receptor (AR) interactions." (PMID 39796040, 2024). "Promoting filamin A cleavage in androgen-dependent prostate cancer may therefore hold therapeutic advantage in preventing tumour metastasis, by increasing cleaved filamin A product nuclear translocation and inhibition of AR." (PMID 38958472, 2024). "In terms of cell populations, we found AR expression to be low in epithelial cells and immune cell populations, but prominent in stromal populations, which comprise a great portion of the tumor mass and might be the main target of bioactive (11-oxy)-androgens." (PMID 39205690, 2024). "Single-cell segmentation analyses revealed that whereas metastatic lesions contain fewer activated-ARhigh cells (~ 20–40% of the tumor cell population) compared with primary tumors (~ 50–90%), those fewer metastatic cells nonetheless exhibited higher levels of activated AR than primary tumor cells." (PMID 38326303, 2024). "These variants lack the ligand-binding domain of the full-length AR, remaining constitutively active and driving tumor growth in the absence of androgens." (PMID 39199550, 2024). "Moreover, PARP-1 is required for AR function, in vivo tumor growth, and maintenance of castration resistance." (PMID 39201718, 2024).
tumor (continued). "Studies have shown that AhR can enhance AR activity, thereby promoting tumor growth." (PMID 39184676, 2024). "In combination with emerging clinical and experimental evidence, we specifically discuss several important and long-term unanswered questions regarding tumor niche roles of stromal AR and highlight future therapeutic strategies by co-targeting epithelial and stromal AR for treating advanced PCa." (PMID 39369165, 2024). "The underlying mechanism for this clinical failure remains unclear, raising a question regarding the tumor niche roles of stromal AR and Shh signaling pathways in regulating prostate epithelial oncogenesis, PCa progression, and CRPC development." (PMID 39369165, 2024). "Once a more widespread clinical utility of these drugs should become evident, our ranking order of tumors according to their AR positivity rates would define the tumor entities that can benefit most from such approaches and which would be best suited for further clinical trials." (PMID 38790919, 2024). "Therefore, simply targeting androgens and androgen receptor signaling pathways cannot block tumor development, and it is necessary to explore other therapeutic directions to enhance clinical treatment efficacy." (PMID 39011396, 2024). "Targeting these epigenetic modifications could improve androgen receptor-targeted therapy and enhance anti-tumor immunity." (PMID 38254784, 2024). "In the context of a comprehensive picture of the AR expression of each tumor under consideration of its genetic heterogeneity, it is of interest to assess the AR status also of DTCs in BM as a surrogate marker of MRD and a potential source of future metastases." (PMID 37902839, 2024). "Additionally, AR suppresses the activity and stemness of male tumor-infiltrating CD8+ T cells by modulating epigenetic and transcriptional programs, such as androgen-driven IFNγ repression." (PMID 39682229, 2024). "On the other hand, the expression of genes TOP1, EGFR, STAT3, NR3C1, VEGFA, and AR was upregulated, which could promote tumor cell growth." (PMID 38297292, 2024). "SAL-induced suppression of MIR503HG enhances the tumor-suppressive effects of AR signaling, suggesting that MIR503HG could serve as a biomarker for BAT responsiveness and as a target for combination therapies with PARP inhibitors." (PMID 39676172, 2024). "Constitutive AR signaling is required for most castration-resistant tumor growth." (PMID 38321455, 2024). "Thus, we cannot confidently state that AR is present in the nucleus of tumor cells, or that the ER that is present is responding to any level of estrogen in the system." (PMID 39684829, 2024). "Interestingly, knocking down MLL and the menin–MLL complex member ASH2L behaves similarly to menin knockdown in reducing AR-target gene expression, cell proliferation, and tumor growth." (PMID 39336822, 2024). "Altogether, these results suggest that, although shorter AR (CAG)n is associated with an increased risk of developing PCa, medium-length alleles may be a risk factor for disease progression once the tumor has developed." (PMID 39594771, 2024). "Furthermore, AhR influences tumor progression independently of AR by regulating genes involved in cell cycle control and apoptosis." (PMID 39184676, 2024). "The oral bioavailability of ARD-2128 in mice reached 67% as it effectively reduced the expression of AR in tumor tissues and inhibited the expression of AR regulatory genes, thereby effectively inhibiting the growth of the tumors in the mice, without any signs of toxicity." (PMID 37847340, 2024). "Accompany with the progression of CRPC, the level of LINC01126 may be chronically elevated, which contributes to enhanced AR‐mediated gene expression program in CRPC tumours." (PMID 38214432, 2024). "Therapeutic strategies that inhibit AR signaling could reduce its tumor-promoting effects and improve clinical outcomes for this group." (PMID 39600743, 2024).
tumor (continued). "We calculated the CCP scores, AR activities, and CRPCsig51 scores for tumor samples in the TCGA-PRAD, DKFZ-PRAD, and Meta-Cohort and found that higher RAECsig scores were significantly correlated with both CCP and CRPCsig51 scores while weakly correlated with negative androgen activities." (PMID 38997406, 2024). "These compounds showed ability to modulate key targets responsible for tumor development, such as aromatase, ER, and AR, and the integrated activities implemented on them may together represent an advantage for treatment at different stages of the disease." (PMID 39338407, 2024). "Having the ability to detect AR, AR splice variant 7 (AR-V7), or PSMA in circulating tumor cells (CTCs) or circulating exosomal cell-free RNA (cfRNA) could be helpful to guide selection of the appropriate therapy for each individual patient." (PMID 38627648, 2024). "Dysregulated AR activity in PCa drives tumour initiation, growth, and progression." (PMID 39529201, 2024). "A suppressor of AR addicted PCa, which can inhibit tumor growth." (PMID 38887275, 2024). "The study found that AR-FL and AR-V7 may serve as prognostic biomarkers for high tumor burden in mCRPC patients prior to treatment with Pluvicto, but none of these parameters correlated with response to PSMA treatment." (PMID 38201308, 2024). "In contrast, in ER-negative breast cancers, AR signalling can drive tumour growth." (PMID 38228924, 2024). "Since GATA3 is an essential gene in ER+ breast cancer cells, we could not use silencing of GATA3 to explore the functional impact of DHT-induced AR-GATA3 interactions on the tumor suppressor role of AR in ER+ breast cancer cells." (PMID 38317241, 2024). "Additionally, optimizing the therapeutic targeting of the AR through ncRNAs raises challenges around delivery specificity, minimizing off-target effects, and understanding patient-specific variables like tumor heterogeneity and prior treatment history." (PMID 39585048, 2024). "In addition to improving control of tumor growth and response to AR inhibition, treatment of Ptenf/fZfp36f/f PCa organoids with DMAPT partially reversed the phenotypic effects of Zfp36 loss." (PMID 39560993, 2024). "Our findings suggest that targeting the AHR could hold therapeutic potential in ccRCC; the activation of this receptor, despite the constitutive HIF1A triggering, is shown to potentiate the tumour suppressor behaviour of both the AR and RB1." (PMID 39336758, 2024). "Blockade of the androgen‐AR axis could shape the tumor microenvironment to support effector T cell differentiation and potentiate the efficacy of PD‐1 blockade." (PMID 38899854, 2024). "On the other hand, although the alpha subunit of the ER is not expressed in TNBC, the beta subunit can be expressed in this type of tumor and could influence, like the AR, in the development of the disease." (PMID 38338747, 2024). "By inhibiting AR signaling, enzalutamide can reduce tumor proliferation and progression." (PMID 39061175, 2024). "In addition to direct tumor kill of AR+ cancer cells through apoptosis and extending doubling time by shifting actively dividing cells to quiescence, ADT plays a role in tumor vascularization and angiogenesis." (PMID 38539538, 2024). "Therefore, many clinical trials and FDA-approved medications target the tumor via AR pathways, such as abiraterone acetate, a type of CYP17A1 inhibitor that blocks the synthesis of androgens, thus affecting tumor growth." (PMID 38398019, 2024). "The sex-divergent effect on tumor size may be related to decreased AR in male mice and/or the observed sex-divergent impact of lead on BMP-7 expression." (PMID 38892327, 2024). "AR chromatin immunoprecipitation with sequencing (ChIP-seq) in NSD2-deficient LNCaP cells showed a dramatic and complete off-loading of the AR protein from over 40,000 genomic sites that comprise over 65% of the tumor cistrome." (PMID 39251788, 2024).
tumor (continued). "The systemic treatment of advanced metastatic breast cancer with agonists of the AR initially used steroidal androgens starting in the 1940s, with as many as 15–30% of patients achieving some tumor regression in spite of their unknown hormone receptor status." (PMID 38339092, 2024). "In the absence of ERα‐expression, these ERα‐binding sites could be hijacked by AR, PR, or GR to maintain expression of genes contributing to tumour cell survival." (PMID 37854018, 2024). "AR was detected in the nucleus of tumor cells and was considered as a sign of androgen activation." (PMID 39768587, 2024). "Moreover, androgen receptor knockout mice develop smaller tumors, and these hormones polarize lung macrophages toward an M2 phenotype that enhances tumor growth through immune suppression." (PMID 39165688, 2024). "AR expression in tumor tissues was assessed after immunofluorescence (IF) staining." (PMID 38965120, 2024). "However, tumor progression due to AR-dependent and AR-independent mechanisms is often observed after some time, and novel treatment strategies are urgently needed." (PMID 38225213, 2024). "Although most tumors progress and maintain AR dependency, approximately 15% to 20% patients will progress where their tumor is indifferent to AR signaling (CRPC-AI) and activate developmental programs related to stemness and pluripotency (phenotypic plasticity)." (PMID 39113611, 2024). "Some studies state that AR signaling has an anti-tumor effect in estrogen-dependent cancers." (PMID 39497884, 2024). "In turn, VEGFC facilitates the androgen-independent reactivation of AR and promotes tumor growth." (PMID 39796040, 2024). "Genomic studies have identified several key genetic aberrations, such as alterations in the androgen receptor (AR) signaling pathway, TMPRSS2-ERG fusion, and mutations in tumor suppressor genes, which contribute to the development and aggressiveness of prostate cancer." (PMID 38992105, 2024). "Enzalutamide directly targets the androgen receptors that drive tumor pathogenesis, competing with native androgens for androgen receptor occupancy, and blocking nuclear translocation of the androgen receptor to prevent transcription of androgen-responsive genes." (PMID 39526247, 2024). "Additionally, SIRT1 deacetylates the coactivator MYST1, enhancing its interaction with AR and NF-κB, which drives aggressive tumor behavior and therapeutic resistance." (PMID 39796040, 2024). "One hypothesis for the DSRCT male prevalence is that elevated testosterone levels in males active the androgen receptor (AR) pathway and drive tumor growth." (PMID 38575753, 2024). "In addition, the influence of both AR and miRNAs on tumor response to treatment suggests that they can be utilized to facilitate the eradication of cancer cells." (PMID 38339416, 2024). "For instance, AR splice variants that lack the ligand-binding domain (LBD) but remain constitutively active have been identified in CRPC, contributing to sustained AR signaling and tumor growth." (PMID 39184676, 2024). "Furthermore, the interaction between AHR and AR signaling creates a synergistic effect in AA patients, enhancing tumor aggressiveness." (PMID 39600743, 2024). "This suggests that gonadal steroid hormones, specifically testosterone, might have a role in tumor development through interaction with the androgen receptor (AR), promoting cell proliferation and tumor progression." (PMID 39768232, 2024). "While a majority of mCRPC remain AR-driven during tumor progression, it has now been shown that a subset of mPC is able to adapt under the therapeutic pressure of hormone therapy by becoming less AR dependent (and thus losing luminal cell markers such as PSA) and developing lineage plasticity." (PMID 38254771, 2024).
tumor (continued). "Stromal AR signaling, particularly within Gli1-lineage cells, may significantly contribute to therapy resistance by supporting epithelial cell survival and tumor growth during ADT." (PMID 39369165, 2024). "These collective findings suggest that EI may exert its influence on attenuating tumor stemness attributes and reversing paclitaxel resistance in BC through the inhibition of the AR/RUNX1 signaling pathway." (PMID 38918989, 2024). "These experiments revealed significantly inhibited tumor growth in both the Ad-AR- and Ad-AR-V7-vaccinated mice as compared to control vaccinated mice, resulting in 8/10 and 7/10 mice remaining tumor-free from Ad-AR-and Ad-AR-V7-vaccinated mice, compared to 1/10 from control vaccinated mice." (PMID 39591176, 2024). "Furthermore, the analysis observed genes related to tumor invasion and metastasis to be upregulated in AR-transfected cells, including Kai-1, SYK, Serpinb, HIF2a, and VEGF, critical players in RCC tumorigenesis." (PMID 39585048, 2024). "Importantly, our model highlights how a nexus of deregulation surrounding FOXM1 drives the tumor biology of AR-low TNBC." (PMID 39335162, 2024). "With AR peptide modification, AR‐ZS/ID‐P NPs were selectively homed and recruited to tumor cells." (PMID 37610511, 2023). "In conclusion, to the best of our knowledge, this is the first work that describes an anti-cancer molecule, Oxy, that in addition to acting as an AI, also modulates both ERs and AR acting as an ERα antagonist and AR agonist, rendering Oxy a more effective anti-tumor profile." (PMID 36677847, 2023). "In this study, using ligand binding and phosphorylation mutagenesis methods, we found that luteolin could inhibit AR protein expression and regulate tumor proliferation and migration by docking site Thr of the AR." (PMID 37716981, 2023). "By understanding the interplay between AR signaling and immune cell function, innovative therapeutic approaches may be developed that enhance anti-tumor immune responses, overcome immune evasion mechanisms, and sensitize CRPC to existing therapies." (PMID 37646236, 2023). "Our results revealed that CBD may be particularly beneficial when combined with the AI exemestane (Exe), since it potentiates the anti-tumor effects of Exe through the modulation of cell death and specific targets, including ERα and androgen receptor (AR)." (PMID 37173983, 2023). "As demonstrated by some authors, in ER-positive BC, AR inhibits tumor proliferation." (PMID 37568977, 2023). "Even thought we did not manage to re-express AR in DU-145 CRPC cells, in primary tumors, due to intra-tumor and inter-patient heterogeneity, the possibility of reverting AR promoter repressive chromatin state may induce AR expression." (PMID 37892208, 2023). "In addition, preclinical evidences suggest that pharmacological inhibition of SPHK can effectively reduce CRPC cell proliferation and xenograft tumor growth by targeting AR and the oncogene MYC39." (PMID 37853018, 2023). "Moreover, AR activation affects the expression of adhesion molecules on endothelial cells, thus facilitating the infiltration of immune cells into the tumor microenvironment." (PMID 37646236, 2023). "Furthermore, M17-B15 exhibits extraordinaryanti-PCa efficacy in vitro and also in mouse xenograft tumor models,demonstrating that AR dimerization disruption by small molecules targetingthe DIP is a novel and valid strategy against PCa." (PMID 37122451, 2023). "They first supported that AR amplification was observed in primary tumour by analysing PDX." (PMID 36203075, 2023). "We found that AR knockdown led to downregulation of Ki67 expression in tumour tissues." (PMID 37326412, 2023). "Additionally, after decreasing the expression of the p160 family and AR, tumor cell proliferation in xenografts of the SD miR-137 group was reduced compared to Scramble (p = 0.012)." (PMID 37298588, 2023). "Interestingly, the AR is expressed in 60–80% of mammary gland tumors, mainly among Luminal A neoplasias." (PMID 37894767, 2023).